ITGA6 (integrin subunit alpha 6)
Diseases named in the same sentence as ITGA6 in open-access papers (continued):
Sharing a sentence is not in itself a finding about the gene and the disease.
tumor (256 papers, 2006 to 2026). "Reciprocally, ovarian fibroblasts educated by ITGA6-high exosomes exhibited cancer-associated fibroblasts (CAFs) phenotypes and enhanced tumor cell proliferation, thereby initiating the early stage of pre-metastatic niche formation." (PMID 40860157, 2025). "Subsequent in-depth functional assays revealed that the E620K mutation of ARHGEF12 as a gain-function mutation promotes OM of GC through tumor-derived ITGA6-high exosomes." (PMID 40860157, 2025). "Mechanistically, ARHGEF12 E620K mutation upregulated ITGA6 expression through Rap1 signaling pathway activation and promoted tumor-derived ITGA6-high exosome formation, which were preferentially uptaken by ovarian fibroblasts." (PMID 40860157, 2025). "Strikingly, homozygous Itga6 deficiency induced a significant delay in tumor formation, with a mean latency of 9 months in α6KO/Brca1p53-KO mice." (PMID 38835038, 2024). "Higher levels of ITGA6 correlate with tumor development, aggressiveness, increased risk of recurrence, poor patient prognosis, shorter event-free survival, and overall survival time in cancer patients." (PMID 39329988, 2024). "As previously indicated, both Thy1 and ITGA6 are potential markers of various cancer stem cells, and their expression is associated with poor differentiation, large tumor growth, lymph node metastases, high invasiveness, and shorter overall survival." (PMID 37444576, 2023). "ITGA6 expression is linked to tumor development, aggressiveness, increased risk of recurrence, poor patient prognosis, shorter event-free survival, and overall survival time in cancer patients." (PMID 37444576, 2023). "The expression of ITGA6 gene was negatively associated with anti‐tumor immune cells, such as plasma cells and CD8+ T cells and most importantly with activated NK cells." (PMID 37392167, 2023). "The ROC analysis further confirmed this, demonstrating that ITGA6 has a strong diagnostic power for distinguishing HCC from non-tumor conditions, even exceeding the value of traditional biomarker, AFP." (PMID 37627184, 2023). "De Archangelis and collaborators categorized integrin α6β4 as a tumor suppressor in the colon of mice models because depletion of the ITGA6 subunit in intestinal epithelial cells causes persistent inflammation leading to tumor growth." (PMID 37444576, 2023). "The abnormal expression of ITGA6 in ccRCC cells has been implicated in promoting tumor cell survival, angiogenesis and resistance to apoptosis." (PMID 37872217, 2023). "High expression of ITGA6 has been associated with an enhanced invasion and tumor-initiating capacity in an MDA-MB-231 model of metastatic BC." (PMID 34502201, 2021). "ITGA6 has been found to associate with tumor cell adhesion, metastasis and resistance to the drugs 32-33, leading to poor prognosis." (PMID 27888613, 2017). "Increased levels of ITGA6 can promote tumor susceptibility and progression." (PMID 37392167, 2023). "Next, the potency of ITGA6 as a non-invasive biomarker was further confirmed through ROC analysis, with an AUC of 0.817, demonstrating robust diagnostic power for distinguishing non-tumor conditions from HCC." (PMID 37627184, 2023). "Tumor-secreted LAMA4 engaged macrophage surface receptor ITGA6 to trigger GATA3 activation and reprogram macrophages toward a pro-metastatic and immunosuppressive phenotype." (PMID 41610310, 2026). "Analysis indicates that ITGA3, ITGA5, and ITGA6 have activating or inhibiting effects on multiple tumor-related pathways." (PMID 41602372, 2026).
tumor (continued). "Proteomic signatures highlighted AREG, JUN, and ITGA6 can track skin damage, while CST5 and PRDX1 correlated with the preservation." (PMID 42143604, 2026). "Here, we demonstrate that GC tumor-derived ITGA6-high exosomes are preferentially uptaken by (ER+) ovarian fibroblasts and those exosome-educated fibroblasts exhibit CAF phenotypes, thereby initiating the early stages of pre-metastatic niche formation of OM." (PMID 40860157, 2025). "We found that CAFs with high ITGA6 expression significantly increased the tumor growth compared to CAFs with EV or NFs." (PMID 40860157, 2025). "Ligand-receptor pairs linked to high-risk tumors, including IL1A_IL1RAP, COL5A1_ITGB1, APP_NCSTN, PLAU_ITGA5, AGRN_ITGB1, and LAMC2_ITGA6, were found to be particularly enriched in tumor regions." (PMID 40021759, 2025). "Using our combination treatment of IL-15 complexes and anti-PD-1 blockade, which induces tumor immunity, we show that the integrin Itga6 is downregulated." (PMID 41373645, 2025). "This is in line with a previous report that shows that Itga6 is regulated by hypoxia, and over-expression leads to tumor metastasis and overall tumor progression." (PMID 41373645, 2025). "Taken together, these data demonstrate that tumor-derived ITGA6-high exosomes are predominantly uptaken by ovarian fibroblasts." (PMID 40860157, 2025). "On the other hand, our analysis identified ITGB1, ITGA5, and ITGA6 as key integrins significantly associated with poor prognosis in HNSC, underscoring their role in driving tumor aggressiveness and therapeutic resistance." (PMID 40021759, 2025). "As previously found by immunostaining of tumor sections, flow cytometry and RT-qPCR analysis further confirmed the reduction of Itga6 expression in α6KO/Brca1p53-KO tumor cells." (PMID 38835038, 2024). "These SMAD3 molecules are secreted into the tumor microenvironment and interact with ITGA6 on the membrane of NSCLC cells, resulting in its hyperactivation." (PMID 38493128, 2024). "ITGA6 has also been associated with GBM subtypes and DNA damage response, while Furin is a component of secretory pathways connected with tumor immunity in various cancers." (PMID 39123468, 2024). "The most pronounced differences in the frequencies of tumor progression-related gene expression were observed in the CTCs expressing ITGB4 with complementary ITGA6 (group 8)." (PMID 38250718, 2024). "Analysis of tumor spheres has revealed co-expression of ITGA6 with the tumor stem cell markers CD133, nestin, and Olig2." (PMID 39239559, 2024). "Tumor volume and weight were increased in mice treated with H460/oe-SMAD3 + Gy or H460/CAFs + Gy, and conversely, H460/oe-SMAD3 + sh-ITGA6 + Gy or H460/CAFs + sh-ITGA6 + Gy led to reduced tumor volume and weight." (PMID 38493128, 2024). "By following up the same patients and by concomitant evaluation of cancer antigen 125 (CA125) levels in patients’ serum, we observed that ITGA6 expression and release in the ascites paralleled tumor progression." (PMID 38658801, 2024). "A tumor-specific version with a smaller molecular weight (70 kDa) of ITGA6, α6p, has been identified in various human cancer cell lines." (PMID 37444576, 2023). "Inhibiting the ITGA6 cleavage into α6p drastically slows down tumor development and migration and improves overall survival." (PMID 37444576, 2023). "Some research studies show that the high level of transcriptions of the ITGA6 can be specifically found in the tumor tissues, displaying an oral‐cancer‐related biomarker." (PMID 37555363, 2023). "Our analysis of single-cell RNA sequencing (scRNA-seq) data revealed the predominant expression of ITGA6 in TECs, suggesting a crucial role in the tumor microenvironment." (PMID 37627184, 2023). "In tumor cells, ITGA6 expression and activity improperly change, promoting signaling pathways that govern carcinogenesis, invasion, angiogenesis, metastasis, immune evasion, stemness, and resistance." (PMID 37444576, 2023).
tumor (continued). "We observed significant over expression of ITGA6 gene in tumor compared to adjacent normal and in BPC tumors compared to GPC tumors." (PMID 37392167, 2023). "ITGA6 has been involved as a key regulator of self-renewal, proliferation, spheroid (anchorage-independent growing ability), and tumor formation capability in cancer stem cells." (PMID 37444576, 2023). "(I) Violin plots showing the expression level of MAGEA4 and ITGA6 in Basal-SCCIS-tumor and Basal-SCCIS-normal subgroups (Wilcoxon test, p_val_adj <0.05)." (PMID 38099574, 2023). "Among potential markers, ITGA6 (integrin alpha-6), and its associated tumor endothelial cells (TECs) has emerged, displaying differing expression patterns in HCC versus non-tumor liver tissues." (PMID 37627184, 2023). "In vivo studies demonstrated that ITGA6 blockade increases tumor latency and survival, suggesting that ITGA6 plays a role in tumor propagation." (PMID 36900358, 2023). "We subsequently confirmed the upregulation of ITGA6 in HCC versus non-tumor tissues across multiple datasets, including GSE114564 and GSE6764." (PMID 37627184, 2023). "Our t-distributed stochastic neighbor embedding (tSNE) plot analysis revealed a division into a total of 53 clusters, and, of particular interest, we observed increased expression of ITGA6, notably within the hepatocytes of tumor tissues." (PMID 37627184, 2023). "ITGA6 has been shown to be elevated in tumor cells despite being expressed at low or undetectable levels in healthy tissues." (PMID 37444576, 2023). "Further validation and analyses revealed consistent upregulation of ITGA6 in HCC, its predominant expression in tumor endothelial cells (TECs), and associations with pro-tumorigenic immune cells." (PMID 37627184, 2023). "Recent studies have reported that high ITGA6 expression enhances invasion and tumor-initiating cell activities in metastatic breast cancer, providing evidence for the value of ITGA6 as cancer stem cell marker." (PMID 38099574, 2023). "On the other hand, we identified repressed genes such as Mdk, Fap, Mmp9, Itga6, and Cxcl12, known as mediators of tumor growth, migration, invasion, and fibrosis." (PMID 36765032, 2023). "Our investigation with scRNA-seq also revealed an intriguing increase in ITGA6 expression within hepatocytes and TECs in tumor tissues, pointing to a cell-specific expression pattern of ITGA6 in HCC." (PMID 37627184, 2023). "The associations we observed with TECs, endothelial cell differentiation, angiogenesis-related pathways, and immune infiltration underline the complex relationship between ITGA6 and the HCC tumor microenvironment." (PMID 37627184, 2023). "Further analysis of ITGA6 expression across 33 cancer types from the TCGA database revealed that ITGA6 was upregulated in tumor tissues compared to normal tissues in 13 different cancers." (PMID 37627184, 2023). "ITGA6 and its ligands mediate the interactions between endothelial cells and tumor cells and other environmental cells." (PMID 35719923, 2022). "YTHDF1/YTHDF3 promotes the tumor growth and progression by recognizing m6A-modified integrin subunit alpha 6 (ITGA6) mRNA and promoting its translation." (PMID 33928028, 2021). "Genome-wide transcriptome analysis and independent-validation of Integrin Subunit Alpha 6 (ITGA6) expression was assessed on mice tumor samples." (PMID 32806777, 2020). "In summary, we mainly evaluated the role of exosomal miR-126 in NSCLC and found that miR-126 overexpression in exosomes blocked NSCLC cell malignant traits and tumor growth in vivo, which was accomplished through the ITGA6-degraded mechanism." (PMID 33317527, 2020). "In mechanism, ITGA6 was a target of miR-126, and exosomal miR-126 weakened these NSCLC cell malignant behaviors and inhibited tumor growth by degrading the expression of ITGA6." (PMID 33317527, 2020). "Landowski at al showed that inhibition of ITGA6 cleavage in vivo decreases osteolytic tumor activity and makes a sclerotic reaction in bone lesions." (PMID 32602654, 2020).
tumor (continued). "ITGA6 has been shown to enhance tumor invasion and the activity of tumor-initiating cells in metastatic breast cancer." (PMID 31847321, 2019). "The qRT-PCR results showed that ITGA6 expression was significantly higher in the GBC tumour tissues than in the corresponding NATs." (PMID 29416013, 2018). "ITGA6 expression has been correlated with expression of migration-related genes, and it can promote the epithelial-mesenchymal transition and tumor invasion." (PMID 29764514, 2018). "Several markers have been defined to isolate GICs from the bulk of the tumor: CD133, encoded by PROM1, CD44, L1CAM or ITGA6." (PMID 29088733, 2017). "To investigate the clinical significance of ITGA3, ITGA6, and TNC in HNSCC, we analysed their associations with tumor stage and lymph node stage using the TCGA-PRAD database." (PMID 28415821, 2017). "We report that ITGA6 is a HIF-dependent target gene and that high ITGA6 expression enhances invasion and tumor-initiating cell activities in models of MBC." (PMID 27001172, 2016). "Our results provide further evidence supporting the notion that blocking ITGA6 expression or using specific agents that target the integrin signaling pathway maximize the efficacy of treatments by sensitizing tumor cells to IR." (PMID 27624978, 2016). "This is based on our observations using in vivo samples that loss of HIFα subunits reduces ITGA6 mRNA expression and that enriching for CD49f+ in PyMT cells enhances tumorsphere formation, tumor initiation and lung metastasis." (PMID 27001172, 2016). "The expression of CD44, CHI3L1 and ITGA6 are all associated with EMT, which were scarcely detected in the AOI as compared to their elevated expression at the tumor core." (PMID 25365423, 2014). "The inflammatory markers IL6 and IL8 as well as the potential HPV receptor ITGA6 were significantly elevated while IL12A was downregulated in the tumour tissues." (PMID 23570247, 2013). "Statistical analysis also suggested Dnmt3a, Itga6, and Shc1, however high fold changes were measured for these genes in tumor cells." (PMID 21464922, 2011). "Notably, integrin alpha-6 (ITGA6), a heterodimeric component of the integrin receptor protein, was significantly upregulated in tumor cells." (PMID 41211420, 2025). "Taken together, these findings suggest that tumor basal stem‐like cells in PSCC may activate the ITGA6/ITGB4 signaling axis through both autocrine and paracrine pathways involving Laminin‐332, thereby promoting tumor invasion." (PMID 40470730, 2025). "Between tumor tissue and normal adjacent tissue, the correlation of glycovariants was very weak to weak, with the only exceptions being the moderate correlation between intratumoral ITGA6–UEA, ITGA2–UEA, and ITGA5–UEA from normal adjacent tissues." (PMID 40287842, 2025). "Strikingly, ITGA6–WFL showed a very weak correlation with all other ITGA6 assays in tumor tissue." (PMID 40287842, 2025). "Moreover, the integrin complex ITGA6+ITGB1 has been correlated with tumor cell adhesion, invasion, and migration." (PMID 39944338, 2025). "However, ITGA6–WFL, with lower signal‐to‐background ratios than others, correlates very weakly, if at all, with all other ITGA6 assays in tumor tissue." (PMID 40287842, 2025). "Notably, the Tum_1 subtype showed elevated expression of LAMC2, which facilitated tumor invasiveness through its interaction with ITGA6/ITGB4." (PMID 40470730, 2025). "Furthermore, ITGA6-high exosome-educated fibroblasts in turn exhibited CAFs phenotypes and promoted tumor cell proliferation, thereby initiating the early stage of pre-metastatic niche formation." (PMID 40860157, 2025). "For example, it is unclear whether MNX1-AS1 exerts its effects through interactions with other proteins and whether ITGA6 regulates additional downstream signalling pathways involved in tumor progression." (PMID 40520020, 2025).
tumor (continued). "Interestingly, mannose‐sensitive ITGA6–ConA performed relatively well in differentiating tumor from normal tissue, while the overall expression of ITGA6 glycovariants was low." (PMID 40287842, 2025). "ITGA6 has been identified as a stemness marker for various tumor stem cells." (PMID 39239559, 2024). "Moreover, the tumor cells often express a shorter version of ITGA6, α6p, originated by proteolysis of the laminin-binding domain from the rest of the molecule." (PMID 39329988, 2024). "Finally, by co-staining peritoneal metastases with anti-ITGA6 and anti-phosphoIGF1Rβ antibodies we observed clear clusters of active IGF1Rβ and ITGA6 co-localization, especially at the site of tumor-mesothelium contacts." (PMID 38658801, 2024). "Notably, the clonogenic potential of luminal progenitors was reduced by Itga6 deletion, potentially contributing to the delayed tumor onset observed in α6KO/Brca1p53-KO mice." (PMID 38835038, 2024). "This suggests that ITGA6 might contribute to the formation of a more immunosuppressive tumor microenvironment, favoring tumor growth and progression." (PMID 37627184, 2023). "Subsequent functional investigation of genes expressed in ITGA6-positive TECs identified enrichment in processes related to endothelial cell differentiation, cadherin binding, and angiogenesis, hinting at the involvement of ITGA6 in tumor angiogenesis and progression." (PMID 37627184, 2023). "In addition, tumor-related gene integrin subunit alpha 6 (ITGA6) was also significantly overexpressed in Basal-SCCIS-tumor cells." (PMID 38099574, 2023). "Furthermore, exogenous TGFβ1 also increased the levels of these three subunits in neutrophils, suggesting that tumor cells up-regulate ITGA6, ITGB1 and ITGB4 in neutrophils through TGFβ1 regulation." (PMID 37056931, 2023). "We observed moderate to strong cytoplasmic and membranous positivity of ITGA6 in tumor cells." (PMID 38099574, 2023). "In addition, ITGA6 and other tumor-related genes were also significantly overexpressed in Basal-SCCIS-tumor." (PMID 38099574, 2023). "Obviously, the cadherin binding related genes including CTNNB1, CDH1, ITGA6, KRT18, and PROM1 were significantly associated with EpCAM, which also implied that EpCAM could play a role in tumor metastasis." (PMID 35517503, 2022). "Collectively, KDM5B could activate the YTHDF3/ITGA6 pathway to enhance the proliferation and growth of tumour cells by inhibiting the expression of miR‐448 in HCC, eventually leading to the occurrence of HCC." (PMID 33829656, 2021). "In short, exosomal miR-126 inhibited tumor growth in vivo by decreasing ITGA6 expression." (PMID 33317527, 2020). "We found ITGA3 significantly associated with primary therapy outcome (p < 0.0001), ITGA6 significantly associated with OS status (p = 0.026), ITGB4 significantly associated with cancer status (p = 0.042) and tumor residual (p = 0.024), ITGB8 significantly associated with chemotherapy (p = 0.020)." (PMID 32765584, 2020). "Moreover, the significantly upregulated DEPs (ITGA1, ITGA6, and ITGB4) that were associated with tumor invasiveness and aggressiveness were confirmed by immunoaffinity analysis in FSH-positive vs. negative NFPAs." (PMID 31832114, 2019). "ITGA6 detection in stools is consistent with its over-expression in tumor cells." (PMID 26895101, 2016). "Based on the observed HIF-dependent regulation of ITGA6 mRNA levels and of CD49f cell surface expression in PyMT, MDA-MB-231 and MCF-7 tumor cells, we next investigated whether ITGA6 is a direct HIF transcriptional target." (PMID 27001172, 2016). "ITGA6 positive tumours showed the strongest association with 63% of cases being ER-, compared to 22% of ITGA6 negative cases (P < 0.0001)." (PMID 22112299, 2011).